THBS1 (thrombospondin 1)
Description:
Adhesive glycoprotein that mediates cell-to-cell and cell-to-matrix interactions. Multifunctional, involved in inflammation, angiogenesis, wound healing, reactive oxygen species (ROS) signaling, nitrous oxide (NO) signaling, apoptosis, senescence, aging, cellular self-renewal, stemness, and cardiovascular and metabolic homeostasis. Negatively modulates dendritic cell activation and cytokine release, as part of an autocrine feedback loop, contributing to the resolution of inflammation and immune homeostasis. Ligand for receptor CD47. Modulates nitrous oxide (NO) signaling via CD47, hence playing a role as a pressor agent, supporting blood pressure (By similarity). Plays a role in endothelial cell senescence, acting via CD47, by increasing the abundance and activation of NADPH oxidase NOX1, and so generating excess ROS. Inhibits stem cell self-renewal, acting via CD47 signaling, probably by regulation of the stem cell transcription factors POU5F1/OCT4, SOX2, MYC/c-Myc and KLF4 (By similarity). Negatively modulates wound healing, acting via CD47 (By similarity). Ligand for receptor CD36. Involved in inducing apoptosis in podocytes in response to elevated free fatty acids, acting via CD36 (By similarity). Plays a role in suppressing angiogenesis, acting, depending on context, via CD36 or CD47. Ligand for immunoglobulin-like cell surface receptor SIRPA. Involved in ROS signaling in non-phagocytic cells, stimulating NADPH oxidase-derived ROS production, acting via interaction with SIRPA. Plays a role in metabolic dysfunction in diet-induced obesity, perhaps acting by exacerbating adipose inflammatory activity; its effects may be mediated, at least in part, through enhanced adipocyte proliferation (By similarity). Plays a role in ER stress response, via its interaction with the activating transcription factor 6 alpha (ATF6) which produces adaptive ER stress response factors (By similarity). May be involved in age-related conditions, including metabolic dysregulation, during normal aging.
Synonyms: TSP; TSP1; THBS; THBS-1; TSP-1
Tractability: Small molecule: a structure with a bound ligand is known; a high-quality ligand is known. Antibody: UniProt places it where antibodies can reach, with high confidence; its Gene Ontology location is reachable by antibodies, with high confidence; UniProt predicts a signal peptide or a membrane-spanning region; the Human Protein Atlas places it where antibodies can reach. PROTAC: ubiquitination databases record sites on it; its protein half-life has been measured; a small molecule that binds it is known.
Target class: Adhesion
Gene: Protein-coding gene on chromosome 15 (39,580,130 to 39,599,466, forward strand). Ensembl gene ENSG00000137801.
Subcellular location: Secreted; Cell surface; Secreted, extracellular space, extracellular matrix; Endoplasmic reticulum; Sarcoplasmic reticulum
Subcellular location (Human Protein Atlas): Endoplasmic reticulum; Plasma membrane; Predicted to be secreted
Pathways (Reactome):
Extracellular matrix organization: Integrin cell surface interactions; Syndecan interactions
Disease: Defective B3GALTL causes PpS
Gene expression (Transcription): RUNX1 regulates genes involved in megakaryocyte differentiation and platelet function
Hemostasis: Platelet degranulation
Metabolism of proteins: O-glycosylation of TSR domain-containing proteins
Signal Transduction: Signaling by PDGF
Gene Ontology:
Molecular function: collagen V binding; endopeptidase inhibitor activity; extracellular matrix structural constituent; fibrinogen binding; fibroblast growth factor binding; fibronectin binding; heparin binding; integrin binding; laminin binding; low-density lipoprotein particle binding; phosphatidylserine binding; protease binding; protein binding; protein homodimerization activity; calcium ion binding; proteoglycan binding; transforming growth factor beta binding; extracellular matrix binding
Biological process: blood coagulation, fibrin clot formation; cell migration; chronic inflammatory response; engulfment of apoptotic cell; immune response; inflammatory response; negative regulation of angiogenesis; negative regulation of antigen processing and presentation of peptide or polysaccharide antigen via MHC class II; negative regulation of apoptotic process; negative regulation of blood vessel endothelial cell migration; negative regulation of blood vessel endothelial cell proliferation involved in sprouting angiogenesis; negative regulation of cell migration involved in sprouting angiogenesis; negative regulation of cell population proliferation; negative regulation of cell-matrix adhesion; negative regulation of dendritic cell antigen processing and presentation; negative regulation of endothelial cell chemotaxis; negative regulation of endothelial cell migration; negative regulation of endothelial cell proliferation; negative regulation of fibrinolysis; negative regulation of fibroblast growth factor receptor signaling pathway; negative regulation of interleukin-10 production; negative regulation of interleukin-12 production; negative regulation of long-chain fatty acid import across plasma membrane; negative regulation of nitric oxide-cGMP mediated signal transduction; negative regulation of plasminogen activation; and 46 more
Cellular component: cell surface; external side of plasma membrane; extracellular exosome; extracellular matrix; extracellular region; fibrinogen complex; platelet alpha granule; secretory granule; endoplasmic reticulum; endoplasmic reticulum lumen; platelet alpha granule lumen; sarcoplasmic reticulum; thrombospondin complex
Genetic constraint (gnomAD): Loss-of-function variants: 28 observed, 127.42 expected, observed/expected ratio (o/e) 0.22, 90% interval 0.16 to 0.3. The synonymous counts are far from expectation, so gnomAD's model fits this gene poorly and the ratio says little. Missense variants: 1,195 observed, 1,612.6 expected, observed/expected ratio (o/e) 0.74, 90% interval 0.71 to 0.78. Synonymous variants: 495 observed, 607.56 expected, observed/expected ratio (o/e) 0.81, 90% interval 0.76 to 0.88.
Homologues: Orthologues: chimpanzee THBS1 (99% identical), macaque THBS1 (99% identical), pig THBS1 (98% identical), rabbit THBS1 (97% identical), dog THBS1 (97% identical), rat Thbs1 (95% identical), mouse Thbs1 (95% identical), guinea pig THBS1 (94% identical), tropical clawed frog thbs1 (82% identical), zebrafish thbs1b (76% identical), zebrafish THBS1 (52% identical), Drosophila melanogaster Tsp (32% identical). Paralogues in human: THBS2 (61% identical), THBS3 (35% identical), THBS4 (35% identical), COMP (32% identical), ISM1 (7% identical).
Diseases named in the same sentence as THBS1 in open-access papers:
THBS1 is named in the same sentence as 396 diseases in open-access papers, as found by Europe PMC text mining. Sharing a sentence is not in itself a finding about the gene and the disease. The quoted sentences say what the papers report.
breast carcinoma (116 papers, 2000 to 2026). "THBS1 expression was positively associated with YAP expression in breast cancer (R = 0.382, p < 0.001)." (PMID 30055645, 2018). "Thbs1 is considered an angiogenesis inhibitor associated to tumor invasion in melanoma, lung cancer, breast cancer and cholangiocarcinoma." (PMID 27167202, 2016). "The high expression of thrombospondin 1 or TSP-1protein observed in kidneys treated with malathion plus estrogen has been associated with wound healing and also with tumor progression of breast cancer metastasis." (PMID 22754462, 2012). "Thrombospondin-1 (Thps1), a potent inhibitor of angiogenesis, is associated with breast cancer metastasis." (PMID 21589862, 2011). "Promoter hypermethylation of THBS1 was detected in brain metastases of solid tumors such as, melanoma, lung, ovarian and breast carcinomas and more recently associated with bad prognosis in penile squamous cell carcinoma." (PMID 22028813, 2011). "The gene encoding thrombospondin (THBS1), which is also frequently methylated in breast cancer, remained unmethylated in all the cells." (PMID 19995452, 2009). "The expression of THBS1 in breast cancer was associated with poor metastasis-free survival." (PMID 37968615, 2023). "The expression of THBS1 in breast cancer associates with poor metastasis-free survival." (PMID 35268340, 2022). "Functional proteomics suggested that collagen proteins, thrombospondin 1 and lumican are differentially expressed across breast cancer subtypes." (PMID 40927672, 2025). "Thrombospondin-1 (THBS1) is highly expressed in breast cancer and melanoma, where it promotes tumor cell adhesion, proliferation, and apoptosis." (PMID 40428349, 2025). "Treatment with anti-THBS1 antibodies promotes ex vivo wound closure in RT+ skin from breast cancer survivors." (PMID 39468077, 2024). "Here, the authors observe compromised wound healing capacity in irradiated skin from breast cancer survivors and highlight THBS1 as a key epigenetically primed wound repair-related gene." (PMID 39468077, 2024). "Previous studies have shown that THBS1 is highly expressed in gastric cancer, breast cancer, melanoma and oral squamous carcinoma, promoting tumor cell adhesion, proliferation, apoptosis, invasion and metastasis." (PMID 37207166, 2023). "The hippo component YAP promotes adhesion plaque and tumor aggressiveness by transcriptionally activating THBS1/FAK signaling in breast cancer." (PMID 37880682, 2023). "Previous research has demonstrated that THBS1 protein is highly expressed in lymphoma, stomach cancer, melanoma, breast cancer and HNSCC, and that it promotes the adhesion, growth, metastasis, and invasion of tumor cells." (PMID 37691922, 2023). "Depleted expression of Kaiso in breast cancer cells modulates the immune signaling molecules within the cargo of exosomes, resulting in increased THBS1 expression and decreased CD47 and SIRPA expression, as well as in decreased phagocytosis by macrophages." (PMID 37190208, 2023). "To determine the clinical significance of Kaiso with the THBS1/CD47/SIRPA signaling axis in breast cancer patients, we analyzed both the TCGA gene expression and protein dataset." (PMID 37190208, 2023). "For example, tRF-17 binds THBS1 (Thrombospondin-1) and reduction in THBS1 expression rescue the effects of tRF-17 inhibition on breast cancer cell viability, invasion and migration." (PMID 37880787, 2023).
breast carcinoma (continued). "For example, calcitriol inhibited thrombospondin 1 (Tsp-1) in a breast cancer model, leading to an increase in VEGF expression." (PMID 37299554, 2023). "The characteristics of increased metastasis by evading immune surveillance in breast cancer can be depicted by the alternative immune signaling and reduced expression of tumor suppressors, such as THBS1." (PMID 37190208, 2023). "For instance, they promote cell proliferation by upregulating fibroblast growth factor 8 (FGF8) and downregulating thrombospondin 1 (TSP1) expression in S115 mouse mammary tumor cells." (PMID 37681860, 2023). "Concentrations of sP-sel and THBS-1 were lower in dabigatran-treated mice 2 days after injection of 4T1 breast cancer cells." (PMID 35295330, 2022). "5-Fu promoted the expression level of THBS1 in human breast cancer cells and colorectal carcinoma cells in a dose-dependent manner." (PMID 35984577, 2022). "Consistent with other effects of tetrac, the latter induces THBS1 in various cancer cells, including colorectal cancer, breast cancer, medullary carcinoma of the thyroid, and pancreatic cancer cells." (PMID 35705962, 2022). "The upregulation of THBS1 was illustrated in different cancer cells such as ovarian cancer, mammary cancer, and thyroid cancer." (PMID 36239104, 2022). "For instance, our identification of thrombospondin-1 as a significantly enriched factor in breast cancer EVs lends evidence to support such antagonistic signaling." (PMID 33435297, 2021). "THBS1 (Thrombospondin-1) as a downstream target of tRF-17, and reduction of THBS1 expression also partially recovered the effects of tRF-17 inhibition on breast cancer cell viability, invasion and migration." (PMID 33912465, 2021). "A study demonstrated that breast tumour cell dormancy was regulated by perivascular niches in the lung, bone marrow and brain, in which endothelial-derived thrombospondin-1 induced sustained breast cancer cell quiescence." (PMID 35006432, 2021). "THBS1 expression was positively associated with TGF-β1 (r = 0.11, p <0.001) and Smad3 (r = 0.39, p <0.001) in breast cancer." (PMID 33912465, 2021). "Taken together, these data suggested that tRF-17-79MP9PP can suppress the TGF-β1/Smad3 signaling pathway by targeting THBS1 in breast cancer cells." (PMID 33912465, 2021). "In 2013, it was demonstrated for the first time that the vascular endothelium induces tumor cell quiescence in an in vivo model of breast cancer dissemination, the THBS1 produced by endothelial cells promotes tumor cell dormancy." (PMID 33738282, 2021). "Co-transfected with THBS1 siRNA markedly abolished the elevated expression of THBS1 induced by the tRF-17-79MP9PP inhibitor in breast cancer cells by a “rescue” experiment." (PMID 33912465, 2021). "Kaplan–Meier survival analysis demonstrated that the overall survival of breast cancer patients with high THBS1 expression was significantly decreased in TCGA breast invasive carcinoma database." (PMID 33912465, 2021). "There is also strong evidence that certain ECM proteins promote cell dormancy, such as the thrombospondin-1 (THBS1) of the microvascular endothelium in breast cancer and osteopontin within the bone marrow in leukemia." (PMID 33738282, 2021). "In breast cancer, it has been demonstrated that exosomal THBS1 facilitates the transendothelial migration of breast cancer cells via disrupting the intercellular integrity of endothelial cells." (PMID 33859239, 2021). "Previous work suggested that the transition of breast cancer cells to dormancy involves accumulation of thrombospondin-1, which can function as an inhibitor of angiogenesis." (PMID 34072967, 2021). "In the present study, we showed that THBS1 expression was positively associated with TGF-β1 and Smad3 in clinical breast cancer specimens by use of public database." (PMID 33912465, 2021).
breast carcinoma (continued). "In sum, we confirmed that tRF-17-79MP9PP significantly suppresses cells malignant activities as a new tumor-suppressor through the THBS1/TGF-β1/Smad3 axis in breast cancer." (PMID 33912465, 2021). "Kaplan–Meier survival analysis indicated that the overall survival in breast cancer patients with high THBS1 expression was significantly reduced in TCGA breast invasive carcinoma database (p = 0.0075)." (PMID 33912465, 2021). "Tetrac was shown to stimulate THBS-1 expression in other types of cancer cells such as breast cancer, medullary carcinoma of the thyroid, and pancreatic cancer." (PMID 32630719, 2020). "THBS1 was first reported in breast cancer in which THBS1 promotes the lung metastasis of breast cancer by facilitating cell adhesion to vessel walls." (PMID 33244454, 2020). "For example neutrophil–derived proteases such as elastase cleave laminin-111 and thrombospondin-1 to awaken dormant breast cancer cells within the lung, and the cleavage products of elastin are highly chemotactic for monocytes." (PMID 33014869, 2020). "Proteomic analyses revealed that thrombospondin-1 (TSP1) was highly expressed in breast cancer cell MDA-MB-231-derived exosomes." (PMID 31817450, 2019). "In human PC3 prostate cancer and MDA-MB-231 breast cancer, bone marrow-derived CD11b+ Gr1+ cells which contain neutrophil populations mainly induce thrombospondin-1 (Tsp-1) in lung premetastatic sites, impairing tumor cell proliferation at the sites." (PMID 31474975, 2019). "Ghajar and colleagues have described a perivascular niche in the lung that traps disseminated mammary carcinoma cells in a dormant state and ascribed a dormancy-inducing activity to endothelial-derived thrombospondin-1." (PMID 29976229, 2018). "Thrombospondin-1 (THBS) is an anti-angiogenic factor and endothelium-derived tumour suppressor that can sustain breast cancer dormancy." (PMID 29662623, 2018). "In summary, these results revealed a model in which YAP regulated FAK Tyr397 phosphorylation through transcriptionally activating THBS1 expression and induced focal adhesion and cell invasion in breast cancer." (PMID 30055645, 2018). "An earlier result showed that THBS1 promoted breast cancer to metastasize to lungs in the polyomavirus middle T antigen transgenic mouse, suggesting that THBS1 plays a role in mammary cancer cell migration." (PMID 27487140, 2016). "A high combined expression score of 5 stromal proteins, namely THBS1, TNC, FN, SPARC and α-SMA, in baseline untreated breast cancers, is associated with shorter survival, while their up-regulation after chemotherapy predicted for poor treatment response." (PMID 27487140, 2016). "It is less clear, however, what roles THBS1 and TNC-associated signaling have in regulation of chemotherapy resistance in breast cancer." (PMID 27487140, 2016). "THBS1 expression is downregulated in advanced non-small cell lung cancer and lymph node metastasis and in breast cancer patients positive for both oestrogen and progesterone receptors." (PMID 25652121, 2015). "Thrombospondin 1 mRNA content is also decreased by androgens in the prostate, bladder and breast cancer cells." (PMID 22605918, 2012). "The YAP/THBS1/FAK and YAP/HMGB1/FAK axes are associated with increased tumor cell proliferation, migration, adhesion, and invasiveness, contributing to poor prognosis in both gastric and breast cancers." (PMID 40895190, 2025). "THBS1 was significantly higher in breast cancer samples from Control rats." (PMID 40806434, 2025). "However, recent studies have reached the contradictory conclusion that THBS1 promotes tumor migration, invasion, and distant metastasis in breast cancer, thyroid cancer, colon cancer, prostate cancer, and melanoma." (PMID 40083708, 2025).